RN7SL865P (RNA, 7SL, cytoplasmic 865, pseudogene)
Gene: Miscellaneous RNA gene on chromosome 12 (115,717,725 to 115,718,013, forward strand). Ensembl gene ENSG00000240205.
Homologues: Orthologues: chimpanzee Metazoa_SRP (99% identical), macaque Metazoa_SRP (92% identical). Paralogues in human: RN7SL1 (84% identical), RN7SL2 (84% identical), RN7SL709P (83% identical), RN7SL3 (83% identical), RN7SL566P (82% identical), RN7SL45P (81% identical), RN7SL567P (81% identical), RN7SL655P (81% identical), RN7SL665P (81% identical), Metazoa_SRP (81% identical), RN7SL14P (81% identical), RN7SL296P (81% identical), and 704 more.